HLA-DPA1 (major histocompatibility complex, class II, DP alpha 1)
Diseases named in the same sentence as HLA-DPA1 in open-access papers (continued):
Sharing a sentence is not in itself a finding about the gene and the disease.
cancer (24 papers, 2017 to 2025). A tumor composed of atypical neoplastic, often pleomorphic cells that invade other tissues. "Decreased HLA-DPA1 expression is associated with poor prognosis, immune infiltration, cancer cell proliferation, and progression in LUAD." (PMID 37899135, 2023). "Overexpression of HLA-DPA1 inhibits cancer cell proliferation, migration, and invasion while promoting cell sensitivity to cisplatin in A549 and A549/DDP cells." (PMID 37899135, 2023). "Using data from both the Cancer Genome Atlas (TCGA) and XENA databases, we calculated that area under the curve for HLA-DPA1 in normal and cancer tissues were 0.86 and 0.842, respectively." (PMID 37899135, 2023). "HLA-DPA1 is abnormally expressed in cancer tissues, contributing to cancer progression." (PMID 37899135, 2023). "In most of the cancers, there was a significant correlation between UBE2C gene expression and HLA‐DMB, HLA‐DOA, HLA‐DPA1, HLA‐PDB1, HLA‐DRA, and HLA‐E." (PMID 38577722, 2024). "We noticed that some MHC class II genes (HLA-DMA, HLA-DPA1, HLA-DPB1, HLA-DRA, HLA-DRB1) were significantly down-regulated in cancer cells with relatively poor differentiation states compared with those with better differentiation states for 5/6 mGC patients." (PMID 37347037, 2023). "Genes in response to interferon gamma, including CCL20, CCL25 and CD74, and antigen presentation-related genes, such as HLA-DPA1, HLA-DRA and HLA-DRB, were significantly upregulated in the cancer cells of immune-rich type tumors." (PMID 36729271, 2023). "The NPS was significantly and positively associated with HLA genes, including TAP1, HLA-E, HLA-DRA, B2M, TAP2, HLA-DPA1, and HLA-DOA in all cancers." (PMID 36170029, 2022). "As for MHC molecules, we found the MHC class II molecules including HLA-DPA1, HLA-DPB1, HLA-DRA, HLA-DRB1, HLA-DQA1, HLA-DQB1 showed a stronger relation with PD-1 than other MHC molecules in some cancer types." (PMID 30607140, 2018). "Notably, HLA-A, HLA-DPA1, HLA-DQB1, HLA-DRA, HLA-DRB1, HLA-DRB5, and HLA-J consistently negatively correlated with the PLK1 expression in the 12 cancer types." (PMID 30631355, 2018). "Several studies suggest that absence of HLA-DPA1 and HLA-DQB1 are correlated with poor prognosis of some cancers." (PMID 35486660, 2022).
infection (5 papers, 2011 to 2023). The state of being infected such as from the introduction of a foreign agent such as serum, vaccine, antigenic substance or organism. "Several upregulated HLA system genes including HPA-DRA and HLA-DPA1 contributed to enrichment of a number of pathways relating to response to infection." (PMID 34658838, 2021). "HLA-DPA1*01:03/DPB1*02:01 [for FAAGLFLRKLTSKEL from DENV serotype 2 and HLA-DRB1*11:01 for the other 2 peptides from serotype 3] could suffer from a relatively higher predilection for DHF following infection with DENV serotypes 2 and 3, respectively." (PMID 29692780, 2018). "Immune-suppressive phenotypes were also detected in cDCs during infection, with notable downregulation of HLA-DR genes HLA-DRA and HLA-DRB1 along with multiple paralogues (HLA-DPA1/B1 and HLA-DQA1/B1) in cDCs but not cytokine/chemokine genes." (PMID 37968278, 2023).
immune disease (3 papers, 2011 to 2025). "The analysis revealed the significant enrichment of genes such as HLA-DQB1, HLA-DPA1, S100A8, SFRP1, CD247, CTSH, and LAMP3, which are linked to inflammatory and immune disease pathways." (PMID 40426861, 2025).
adenocarcinoma (2 papers, 2021). A common cancer characterized by the presence of malignant glandular cells. "A high expression level of HLA-DPA1 was significantly associated with adenocarcinoma histology (p = 0.03), whereas the expression level of IFNB1 was significantly lower in male patients (p = 0.05)." (PMID 34209514, 2021).
psychiatric disorder (2 papers, 2016 to 2026). A disorder characterized by behavioral and/or psychological abnormalities, often accompanied by physical symptoms. "Quantitative Trait Locus (QTL) analyses and brain gene expression studies suggest that HLA-DPA1 may contribute to immune-related alterations in psychiatric disorders, indicating its genetic variation or expression levels might influence MDD susceptibility or severity." (PMID 41601671, 2026).
gastrointestinal tumor (1 paper, 2024). "We further found NOTCH3 levels in gastrointestinal tumor to correlate with markers of Dendritic cell(HLA-DPB1, HLA-DRA, HLA-DPA1, BDCA-4), Tfh(T-bet, STAT4, STAT1, TNF-α), Treg cells (FOXP3, CCR8, STAT5B, TGFβ) and T cell exhaustion (PD-1, CTLA4, LAG3, TIM-3)." (PMID 38906903, 2024).
kidney disease (1 paper, 2021). "Our findings indicate that a high expression of different co-DEGs was correlated with a low glomerular filtration rate in kidney disease samples (IL10RA, HLA-DPA1, r = −0.490, p < 0.001; IRF8, HLA-DRA, r = −0.500, p < 0.001; HLA-DPB1, r = −0.510, p < 0.001; HLA-DMA, r = −0.480, p < 0.001)." (PMID 34692653, 2021).
HLA-DPA1 also shares sentences with these, for which no sentence is quoted: Autoimmunity (3 papers); Hypertension (3); rheumatoid arthritis (3); atherosclerosis (2); glioma (2); inflammatory bowel disease (2); sarcoma (2); Stroke (2); Achalasia (1); acute myeloid leukemia (1); adrenal cortical tumors (1); autism (1); B-cell lymphoma (1); basal cell carcinoma (1); berylliosis (1); breast invasive carcinoma (1); cervix tumors (1); childhood asthma (1); colon carcinoma (1); colorectal cancer (1); colorectal tumor (1); cutaneous leishmaniasis (1); dementia (1); Epstein-Barr virus infection (1); Ewing sarcoma (1); gastric cancer (1); granulomatosis with polyangiitis (1); Graves disease (1); gynecological tumors (1); heart disease (1).
A further 29 diseases each share a sentence with HLA-DPA1 in 1 paper.